MFAP2 (microfibril associated protein 2)
Diseases named in the same sentence as MFAP2 in open-access papers (continued):
Sharing a sentence is not in itself a finding about the gene and the disease.
tumor (continued). "For example, among 10 markers that are localized in the tumor stroma according to IHC images, 4 genes (MFAP2, MFAP5, PDGFRA, CDH11) are specifically represented in “Fibroblasts”, while the remaining markers are expressed in both cell types." (PMID 36263012, 2022). "sc-CAFs-NFs analysis revealed a significant increase in CAFs expression of 3 exiting marker genes (FAP, COL11A1 and POSTN) and 2 newly proposed markers (COL6A3 and MFAP2) in all tumor types we studied." (PMID 36263012, 2022). "Immunohistochemical staining has shown that the MFAP2 protein expression in tumor tissues is significantly higher than that in normal tissues." (PMID 36530974, 2022). "This study was expected to provide a theoretical basis for gaining insight into the role of MFAP2 in tumor immunotherapy." (PMID 35211173, 2022). "In the next study, we intend to further verify the effect of MFAP2 on tumor cell proliferation, migration, and invasion and explore the molecular regulation mechanism." (PMID 35211173, 2022). "Various authors have shown that MFAP2 overexpression promotes tumor progression by activating cellular signaling pathways." (PMID 36530974, 2022). "Immunohistochemistry and western blotting results showed that MFAP2 protein expression in tumor tissues was significantly higher than that in adjacent normal tissues." (PMID 36530974, 2022). "Recent studies have shown that MFAP2, an effective prognostic molecule for various tumors, is associated with tumor occurrence and development and may be involved in remodeling the extracellular matrix and regulating proliferation, apoptosis, invasion, tumor cell metastasis, and tumor angiogenesis." (PMID 36530974, 2022). "In vivo, MFAP2 knockdown reduced tumor volume by 62.4% and suppressed the autophagy-Wnt axis." (PMID 42193330, 2026). "The inconsistency between in vitro and in vivo results suggests that the function of MFAP2 in ESCC might be related to the tumor microenvironment." (PMID 40657371, 2025). "Immunohistochemistry results showed that MFAP2 was located in extracellular matrix, cytoplasm, and nucleus, indicating the tumor microenvironment could alter MFAP2 localization in esophageal squamous carcinoma cells and may play non-extracellular matrix roles." (PMID 40657371, 2025). "All these data indicated MFAP2 may aggravate tumor progression through PTGS2 signaling which has been proven to be a tumor driver." (PMID 40657371, 2025). "In addition, we investigated the relationship between MFAP2 transcription and several clinical features, and our findings revealed that MFAP2 gene expression was related to ki67 expression (P = 0.007) and tumor grade (P = 0.030)." (PMID 38822944, 2024). "There is mounting evidence that MFAP2 promotes tumor growth." (PMID 38822944, 2024). "However, it was found that MFAP2 is necessary for depositing EGFL7 into microfibrils, which is crucial for vascular development, showing that MFAP2 is important in tumor angiogenesis." (PMID 36530974, 2022). "In addition, MFAP2 is important in tumor cell apoptosis, proliferation, angiogenesis, invasion, and prognosis." (PMID 36530974, 2022). "The effects revealed comparable daily tissues by the stage of MFAP2 expression in tumor tissue." (PMID 35356627, 2022). "MFAP2 may be an important biomarker with prognostic value and has the potential to be a target for tumor immunotherapy." (PMID 35211173, 2022). "By qPCR, MFAP2 expression was validated in four kinds of tumor tissue samples." (PMID 35211173, 2022). "Combining multiple algorithms, we found that MFAP2 was closely related to the immune infiltration profile in tumor tissue, affecting not only the proportion of immune cells but also the expression levels of many immune-related genes, including immune checkpoints." (PMID 35211173, 2022).
tumor (continued). "This review aimed to summarize MFAP2 expression in tumor cells and its role in tumor cell proliferation, apoptosis, invasion, and metastasis and discuss its possible signaling pathways to provide new ideas for tumor therapy." (PMID 36530974, 2022). "The inhibition of MFAP2 may inhibit the proliferation of tumor cells, and then inhibit the progress of tumor, which plays an important role in tumor treatment." (PMID 36530974, 2022). "The results showed that MFAP2 expression was negatively correlated with tumor neoantigen in UCEC." (PMID 35211173, 2022). "Considering the importance of neovascularization for tumor progression, targeted MFAP2 therapy may play an active role in tumor therapy, especially for vascular rich tumors." (PMID 36530974, 2022). "Nevertheless, MFAP2 remains a potential tumor suppression feature based on previous results." (PMID 33816256, 2021). "Therefore, MFAP2 emerges as a promising therapeutic target for anti-tumor efforts." (PMID 41716634, 2025). "Furthermore, it was observed that MFAP2 displayed a negative correlation not only with tumor mutational burden (TMB), a recognized biomarker for PD-1/PD-L1 immunotherapy, but also with PD-L1 in samples of TNBC." (PMID 38822944, 2024). "Also, the basal levels of MFAP2 expression in various tumor cell lines were assessed." (PMID 35211173, 2022). "Therefore, further studies are needed to reveal MFAP2’s role and mechanism in tumor angiogenesis." (PMID 36530974, 2022). "Therefore, MFAP2-targeted therapy may play an important role in adult tumor therapy with minimal collateral damage." (PMID 36530974, 2022). "Targeting MFAP2 may play an important role in tumor therapy." (PMID 36530974, 2022). "Therefore, MFAP2 expression in tumor tissues and its prognostic relevance were determined." (PMID 36530974, 2022). "To further evaluate the clinical significance of MFAP2 in ESCC, we systematically analyzed the relationship between MFAP2 expression and lymph node metastasis, tumor size and survival time." (PMID 40657371, 2025). "MFAP2 expression has been increased and verified in many unbiased coalitions in TCGA-STAD tumor tissues." (PMID 35356627, 2022). "However, MFAP2’s specific mechanism in these tumor processes remains unclear." (PMID 36530974, 2022). "The expression levels of PHTF2, MFAP2, INHBA, TSPAN9, and CCL26 (p < 0.05) displayed tumor stage-dependent alterations." (PMID 34456964, 2021). "Consistent with our statistical analysis, quantitative PCR confirmed the upregulation of BST2 and MFAP2 and the downregulation of KRT31 when samples of HNSCC were compared to tumor-free surgical margins." (PMID 19014460, 2008). "This study showed that although MFAP2 expression was elevated in ESCC and high levels of MFAP2 were closely related to poor patient prognosis, overexpressing MFAP2 in ESCC cells only enhanced tumor growth in vivo rather than in vitro." (PMID 40657371, 2025). "The results demonstrated that MFAP2 expression was not significantly different between metastasis and non-metastasis groups, but was correlated with tumor stage." (PMID 40657371, 2025). "Despite the availability of reasonably accurate m1A detection methodologies for monitoring its role in tumor development, the precise m1A modification sites remain elusive, particularly in cases such as CRC where m1A has been shown to regulate the MFAP2/CLK3 axis." (PMID 38291517, 2024). "Previous studies have shown that MFAP2 was involved in controlling growth factor signal transduction and interacted with the TGF‐β superfamily members to promote tumour progression, particularly in relation to epithelial‐mesenchymal transition (EMT) and ECM remodelling." (PMID 37635348, 2023).
tumor (continued). "The MFAP2 expression level was significantly correlated with lymph node metastasis, tissue type, and tumor focus type, and its downregulation induced BCPAP and TPC-1 cell apoptosis." (PMID 36530974, 2022). "In addition to participating in tumor cell proliferation, MFAP2 plays an important role in tumor invasion and metastasis through EMT in tumor cells." (PMID 36530974, 2022). "Mechanistically, MFAP2 overexpression may lead to ECM remodeling, epithelial-mesenchymal transformation, and promotion of tumor cell migration via the integrin α5β1/FAK/ERK; nevertheless, the specific mechanisms remain unclear." (PMID 36204318, 2022). "Since MFAP2 is an important component of extracellular matrix, more and more in-depth studies are needed to confirm whether MFAP2 can inhibit the EMT of tumor cells and inhibit the invasion and metastasis of tumor cells in all tumors." (PMID 36530974, 2022). "Moreover, significant differences were found in the expressions of INHBA, CCL26, MFAP2, TSPAN9, and PHTF2 in tumor stage based on TCGA-ESCA, suggesting their prognostic value in ESCC tumor development." (PMID 34456964, 2021).
metabolic disease (4 papers, 2016 to 2025). A congenital disorder (due to inherited enzyme abnormality) or acquired (due to failure of a metabolically important organ) disorder resulting from an abnormal metabolic process. "Multiple studies have confirmed the association between MFAP2 mutation and various conditions in humans, including hemostasis and thrombosis, metabolic disease, thoracic aneurysms, and osteopenia." (PMID 38822944, 2024).
MFAP2 also shares sentences with these, for which no sentence is quoted: glioblastoma (3 papers); head and neck cancer (2); infection (2); metabolic syndrome (2); pancreatic cancer (2); systemic sclerosis (2); Alzheimer disease (1); amyotrophic lateral sclerosis (1); anaphylaxis (1); Arthritis (1); bladder cancer (1); bladder urothelial carcinoma (1); cervical cancer (1); COVID-19 (1); diabetes (1); digestive system tumors (1); epilepsy (1); esophageal squamous cell carcinoma (1); Hyperglycemia (1); kidney cancer (1); laryngeal squamous cell carcinoma (1); leiomyoma (1); leukemia (1); lung carcinoma (1); lymphoma (1); monocytopenia (1); multiple sclerosis (1); myeloma (1); pancreatic adenocarcinoma (1); paraganglioma (1).
A further 7 diseases each share a sentence with MFAP2 in 1 paper.